TGIF2 (TGFB induced factor homeobox 2)
Diseases named in the same sentence as TGIF2 in open-access papers (continued):
Sharing a sentence is not in itself a finding about the gene and the disease.
colorectal cancer (3 papers, 2019 to 2025). A primary or metastatic malignant neoplasm that affects the colon or rectum. "Nuclear PKM2 binds to TGFB induced factor homeobox 2 (TGIF2), which is a transcription factor of Cadherin-1 (CDH1), and represses CDH1 transcription and stimulates the mesenchymal marker, vimentin, during EMT both in in vitro and in vivo colorectal cancer models." (PMID 31027222, 2019).
glioblastoma (3 papers, 2022 to 2024). The most malignant astrocytic tumor (WHO grade IV). "Specifically, elevated TGIF2 expression was observed in low-grade glioma (LGG) and glioblastoma (GBM) compared to normal brain tissues." (PMID 38629068, 2024). "Studies have also reported that EZH2 is involved in a novel miR-490-3p/TGIF2/TGFBR1 axis inducing migration and EMT in glioblastomas." (PMID 36230759, 2022).
non-small cell lung carcinoma (3 papers, 2020 to 2022). A group of at least three distinct histological types of lung cancer, including non-small cell squamous cell carcinoma, adenocarcinoma, and large cell carcinoma. "In non-small-cell lung cancer, TGIF2 contributed to cell proliferation, migration, invasion, and epithelial-mesenchymal transition." (PMID 34965271, 2021).
breast carcinoma (2 papers, 2003 to 2019). "Generally, our study identified three mRNAs (TBX21, TGIF2, and CYCS) that were significantly altered between high‐ and low‐risk patients with breast cancer." (PMID 30632703, 2019).
gastric cancer (2 papers, 2018 to 2024). A primary or metastatic malignant neoplasm involving the stomach. "There are also some reports describing other mechanisms of TGIF2 regulation by binding with some microRNAs such as miR-148a and miR-34a, which are contributing to skin and gastric cancer progression, respectively." (PMID 30333907, 2018).
melanoma (2 papers, 2015 to 2021). A malignant, usually aggressive tumor composed of atypical, neoplastic melanocytes. "The increase in FUT8 expression in melanoma cells was found to be transcriptionally regulated by TGFβ-induced factor homeobox 2 (TGIF2)." (PMID 34440905, 2021).
acute myeloid leukemia (1 paper, 2024). Acute myeloid leukemia (AML) is a group of neoplasms arising from precursor cells committed to the myeloid cell-line differentiation. "TGIF2 has been studied much less in YAPoff cancers, although the paralog TGIF1 suppresses acute myeloid leukemia consistent with our results in neural/neuroendocrine YAPoff cancers." (PMID 39172021, 2024).
Anxiety (1 paper, 2022). Intense feelings of nervousness, tension, or panic often arise in response to interpersonal stresses. "When it comes to the specific role of TGIF2 in autism, the experimental results suggested that AAV9‐mediated TGIF2 significantly alleviated the autism‐like symptoms, such as anxiety, mobility disturbance, impaired learning and memory abilities, and social avoidance." (PMID 35592894, 2022).
astrocytoma (1 paper, 2024). "Kaplan-Meyer analysis revealed that higher TGIF2 expression associated with worse OS in subgroups including age >60, age ≤60, male, female, Race (White), WHO grade (G3), 1p/19q codeletion status (non-codel), histological type (astrocytoma), and primary therapy outcome (PD)." (PMID 38629068, 2024). "For DSS, patients with higher TGIF2 expression had worse DSS in subgroups such as age >60, age ≤60, male, female, race (White), WHO grade (G3), 1p/19q codeletion status (non-codel), histological type (astrocytoma), primary therapy outcome (PD) and primary therapy outcome (SD)." (PMID 38629068, 2024).
autism (1 paper, 2022). Persistent deficits in social interaction and communication and interaction as well as a markedly restricted repertoire of activity and interest as well as repetitive patterns of behavior. "Herein, the potential biological involvement of TGIF2 loss in autism development attracted our interests." (PMID 35592894, 2022). "In this study, the authors report that epigenetic downregulation of TGIF2 is linked to neuronal apoptosis and the neuronal disorder symptoms in mice with autism through the inactivation of the Wnt/β‐catenin pathway." (PMID 35592894, 2022). "This body of evidence suggests that TGIF2 overexpression alleviates developmental delay and autism‐like symptoms in VPA mice." (PMID 35592894, 2022). "Restoration of TGIF2 alleviates neuronal apoptosis and autism‐like symptoms in mouse through activating the Wnt/β‐catenin pathway." (PMID 35592894, 2022). "Restoration of TGIF2 alleviates neuronal apoptosis and autism‐like symptoms in mouse by activating the Wnt/β‐catenin pathway." (PMID 35592894, 2022). "This study suggests that TGIF2 is downregulated in autism, which is possibly regulated by LSD1/H3K4me1." (PMID 35592894, 2022). "This body of evidence suggested that TGIF2 plays a protective role against neuronal apoptosis and neural impairment in autism." (PMID 35592894, 2022). "Adenovirus‐mediated overexpression of TGIF2 suppressed autism‐like symptoms and neuronal apoptosis in autistic mice." (PMID 35592894, 2022). "In conclusion, this study demonstrates that TGIF2 is downregulated in autism, which is possibly regulated by LSD1/H3K4me1." (PMID 35592894, 2022). "The present study was performed to validate the expression and functions of TGIF2 in autism and the molecular mechanism." (PMID 35592894, 2022). "This study aimed to elucidate the correlation of TGIF2 with autism, a neurodevelopmental condition which presents with severe communication problems." (PMID 35592894, 2022). "The functions of TGIF2 in autism‐like symptoms in mice were examined by behavioral tests and histological examination of their hippocampal tissues." (PMID 35592894, 2022). "Therefore, the authors surmised that there is an interaction between LSD1, H3K4me1, and TGIF2 in the neural impairment and development of autism." (PMID 35592894, 2022). "Therefore, it can be inferred that the downregulation of TGIF2 in autism might be attributed to LSD1‐mediated suppression of the H3K4me1 modification at the promoter of TGIF2." (PMID 35592894, 2022). "Therefore, we postulated that the aberrant TGIF2 expression might be correlated with the pathogenesis of autism." (PMID 35592894, 2022). "The findings suggest that TGIF2 may serve as a candidate tool for the management of autism." (PMID 35592894, 2022). "Therefore, TGIF2 possibly activates the Wnt/β‐catenin to restore the neural function in autism." (PMID 35592894, 2022). "This research suggests that the downregulation of TGIF2, possibly regulated by LSD1/H3K4me1, is correlated with neuronal apoptosis and development of autism in mice through the inactivation of the Wnt/β‐catenin pathway." (PMID 35592894, 2022).
depression (1 paper, 2025). "Through comprehensive molecular regulatory network analysis, transcription factors such as ATF1, IRF1, HBP1, DRAP1, TGIF2, and TFDP1 were identified as potential regulatory factors in depression, warranting further exploration." (PMID 40370590, 2025).
diabetes (1 paper, 2022). "When we analyzed TGFβ-associated genes, we were astonished that several triggers like TGFβ2 and TGFBI were significantly activated by diabetes, while several suppressors like TGIF1 and TGIF2 were significantly deactivated by diabetes." (PMID 35935990, 2022).
diabetic kidney disease (1 paper, 2022). Progressive kidney disorder caused by vascular damage to the glomerular capillaries, in patients with diabetes mellitus. "Based on the results of transcriptomics, the pathogenesis of diabetic kidney disease may involve 11 candidate differential genes: Egr1, Foxo3, Pik3r3, Fgf1, Sost, Wnt10a, Tgif2, Akt2, Mep1b, Col1a1, Apoe." (PMID 36249745, 2022).
HIV-1 infection (1 paper, 2021). The type species of lentivirus and the etiologic agent of acquired immunodeficiency syndrome (AIDS). "In this study, we investigated the role of miRNAs in HIV-1 infection and found that HIV-1 infection upregulated miR-210-5p in order to suppress TGIF2, which resulted in G2 arrest." (PMID 34965271, 2021). "Luciferase reporter assays and western blotting confirmed that a target protein of miR-210-5p, TGIF2, is regulated by HIV-1 infection." (PMID 34965271, 2021). "In conclusion, we identified a mechanism whereby miR-210-5p, which is induced upon HIV-1 infection, targets TGIF2." (PMID 34965271, 2021). "Therefore, we searched the targeted gene of miR-210-5p during HIV-1 infection and found that TGIF2 is a target of miR-210-5p and was regulated during HIV-1 infection." (PMID 34965271, 2021).
holoprosencephaly (1 paper, 2014). Holoprosencephaly (HPE) is a complex brain malformation resulting from incomplete cleavage of the prosencephalon, occurring between the 18th and 28th day of gestation, and affecting both the forebrain and face, which results in neurological manifestations and facial anomalies of variable severity. "The contribution from Tgif2 in holoprosencephaly (failure of the embryonic forebrain to completely divide into two hemispheres) is still controversial." (PMID 25191221, 2014).
leiomyoma (1 paper, 2007). A well-circumscribed benign smooth muscle neoplasm characterized by the presence of spindle cells with cigar-shaped nuclei, interlacing fascicles, and a whorled pattern. "They included several genes such as NR2F1, PNN, Smad4, Smad5, STAT5B, JUN, TGIF2, and ATF1 that were over-expressed while RUNX3, STAT1, STAT6, EGR3, GAS7, Smad1, and EDF1 were underexpressed in leiomyomas as compared to keloid/incisional scars." (PMID 17718906, 2007).
liver fibrosis (1 paper, 2021). "Finally, we showed that miR-34a promoted EMT and liver fibrosis in PBC by targeting the TGF-β1/smad pathway antagonist transforming growth factor-beta-induced factor homeobox 2 (TGIF2)." (PMID 33977112, 2021).
lymph node metastasis (1 paper, 2019). "We found that high TGIF2 expression was closely correlated with tumor growth, lymph node metastasis, and survival of patients with LUAD." (PMID 31871777, 2019).
osteoarthritis (1 paper, 2021). A noninflammatory degenerative joint disease occurring chiefly in older persons, characterized by degeneration of the articular cartilage, hypertrophy of bone at the margins and changes in the synovial membrane. "Moreover, in vitro study has implicated miR34a in osteoarthritis synovial cell apoptosis via regulation of TGIF2." (PMID 34768615, 2021).
ovarian tumors (1 paper, 2018). "However, they did not mention the TGIF2 protein expression and its relation to the ovarian tumor progression clearly." (PMID 30333907, 2018).
rectal cancer (1 paper, 2008). A primary or metastatic malignant neoplasm that affects the rectum. "On basis of integrative analysis this study identified one well known CRC gene (SMAD2) and several other genes (EFNA1, BOP1, TGIF2 and STMN3) that possibly could be used for rectal cancer characterization." (PMID 18959792, 2008). "We identified one well known CRC gene (SMAD2) and several other genes (EFNA1, BOP1, TGIF2 and STMN3) that possibly could be used for rectal cancer characterization." (PMID 18959792, 2008).
retinoblastoma (1 paper, 2024). A malignant tumor that originates in the nuclear layer of the retina. "TGIF2 was included in the screen because it is a YAP-induced target gene in SHP77 SCLC cells, but it was not induced by YAP in Y79 retinoblastoma cells." (PMID 39172021, 2024).
tumor (22 papers, 2012 to 2025). "miR-34a’s inhibition of TGIF2 was demonstrated to impede these mechanisms, thereby lowering tumor invasion and metastatic potential in Osteosarcoma cells." (PMID 40429954, 2025). "TGIF2 is related to tumor growth, primarily through the stimulation of EMT, which promotes cell motility and metastasis." (PMID 40429954, 2025). "Taken together, the coordination of TGIF2/SOX2 promotes subcutaneous tumor size and liver metastasis by activating EMT and EGFR/MAPK signaling." (PMID 39781447, 2025). "TGIF2 also impacted pathways related to tumor immunity, including cytokine cytokine receptor interaction, signaling by interleukins, inflam pathway, chemokine signaling pathway, toll-like receptor signaling pathway, and Pd-1 signaling." (PMID 38629068, 2024). "The impact of TGIF2 on tumor immune infiltration was assessed through Estimate, ssGSEA, and Spearman analysis." (PMID 38629068, 2024). "MiR-29c inhibits tumor growth by regulating TGFB-induced factor homeobox 2 (TGIF2), CAMP-responsive element binding protein 5 (CREB5), and V-Akt murine thymoma viral oncogene homolog 3 (AKT3)." (PMID 37298314, 2023). "TGIF2 mRNA was highly expressed in 23 HBV-associated HCC patients’ tumors, and its protein expression was higher in tumor tissue from three randomly selected tumors." (PMID 33714261, 2021). "Namely, TGIF2 was expressed in the tumor cells that expressed basal cell marker p63 and epithelial cell marker cytokeratin." (PMID 30333907, 2018). "TGIF1 and TGIF2 that are repressors of tumor suppressor SMAD proteins are also differentially methylated." (PMID 28423671, 2017). "Briefly, TGIF2 overexpression was closely associated with T stage (P=0.011), lymph node metastasis (P=0.032), and TNM stage (P=0.028), whereas SOX2 overexpression was associated with tumor size (P=0.029) and T stage (P=0.026)." (PMID 39781447, 2025). "However, SOX2 silencing or erlotinib treatment significantly reversed TGIF2 overexpression-promoted increase in tumor size (TGIF2-OE vs. TGIF2-OE/shSOX2; TGIF2-OE vs TGIF2-OE/Erlotinib)." (PMID 39781447, 2025). "Furthermore, in the GSE14805 dataset, we identified 2954 DEGs, including 1369 upregulated and 1585 downregulated genes, with TGIF2 significantly upregulated in the tumor group." (PMID 38629068, 2024). "This indicates that TGIF2 could recruit different HDACs to repress E-cadherin expression in different cancer types, reflecting tumor heterogeneity." (PMID 36647029, 2023). "In OS, TGIF2 has also been reported to be involved in tumor progression." (PMID 32709240, 2020). "Silencing TGIF2 significantly reduced tumor growth, which could be rescued by the ectopic expression of shRNA-resistant TGIF2." (PMID 31871777, 2019). "Importantly, miR-34a targets several gene products associated with advanced PCa, including c-Myc, MET and Axl in tumor cells and Tgif2 in the bone microenvironment." (PMID 26313360, 2015). "The consequence was inhibited tumor cell motility, reduced tumor growth, and inhibited metastasis formation, with an associated down-regulation of miRNA oncogenic target genes, such as C-MYC, E2F2, CDK6, and TGIF2." (PMID 23091478, 2012). "Importantly, lymph node metastases were enriched in EMT-related gene programs and transcriptional circuits such as those driven by ZEB1, TWIST1, and TGIF2, which are known to fuel the mesenchymal shift in tumor cell states facilitating dissemination and survival in secondary sites." (PMID 41279557, 2025). "Furthermore, decreased levels of OCT4 and SOX2 were observed in TGIF2-silenced tumor cells, which could also be rescued by ectopically expressed TGIF2." (PMID 31871777, 2019). "Furthermore, TGIF2 was expressed in the tumor cells that expressed PKM2." (PMID 30333907, 2018). "Functionally, miR-490-3p acts as a tumor suppressor, inhibiting migration and EMT by directly targeting the upstream receptor TGFBR1 and the downstream transcription factor TGIF2 within the TGF-β signaling pathway." (PMID 40565099, 2025).
tumor (continued). "In addition, a limited dilution xenograft assay revealed that 105 of TGIF2-silenced H1299 cells xenografted in NOD/SCID mice showed a dramatically decreased incidence of initiating a tumor when compared with that of control cells, which could also be restored by increasing TGIF2 levels." (PMID 31871777, 2019). "In vitro studies using non-colonic cell lines have indicated that miR-148a exerts a tumor suppressive function by targeting several genes such as PXR, TGIF2, MSX1, CDC25B, DNMT1 and DNMT3b." (PMID 23056401, 2012). "On the contrary, TFH cells were associated with anti-tumor immunity, and the negative correlation observed between TGIF2 and TFH cells suggests a potential contribution of TGIF2 to tumor immune escape." (PMID 38629068, 2024). "Accidently, there was a negative correlation between miR-424-5p and TGIF2 mRNA expression in these tumor tissues." (PMID 33714261, 2021). "Furthermore, elevated TGIF2 expression positively correlated with cell cycle regulation, DNA synthesis and repair, extracellular matrix (ECM) components, immune response, and several signaling pathways that promote tumor progression." (PMID 38629068, 2024). "Notably, TGIF2 expression levels in 21 tumor tissues were significantly higher than in corresponding normal tissues." (PMID 38629068, 2024). "Some show marked differential expression in a single non-SHH subgroup,such as NFIA (Group 3 tumours) and FGF13 (Group 4 tumours), orin more than one subgroup (e.g. TGIF2 and MYT1L), suggestingthat these genes may be relevant to MB in general." (PMID 24252690, 2013).